TNF (tumor necrosis factor)
Diseases named in the same sentence as TNF in open-access papers (continued):
Sharing a sentence is not in itself a finding about the gene and the disease.
tumor (continued). "Exogenous TNF-α can provide support for the recruitment of bone marrow-derived mesenchymal stromal cells (BM-MSCs) into the tumor microenvironment, wherein these cells are differentiate into tumor-resident MSCs that overexpress CCR2 ligands." (PMID 29915688, 2018). "The transformation of smooth muscle cells of the uterus into abnormal, immortal cells, capable of clonal division, is the main component of all pathways leading to UF tumor formation and tumor necrosis factor α (TNF-α) is believed to be one of the key factors in this field." (PMID 30518097, 2018). "Previous studies showed that tumors produce tumor necrosis factor alpha, granulocyte colony-stimulating factor, interleukin-1 (IL-1), and IL-6, which may influence tumor-related SIR." (PMID 28744596, 2018). "Other studies found similar toxicities associated with systemic TNF-alpha administration, with little or no favorable achievement in tumor response." (PMID 30170620, 2018). "This discrepancy could be explained by the fact that TNFα exerts its anti-tumor effects in vivo via the death receptor-dependent apoptotic pathway, like TRAIL, but also via its anti-angiogenic effects, that are critical for its anti-cancer activity." (PMID 29493296, 2018). "Of interest is that specific delivery of TNF-alpha to tumor sites promotes anti-tumor effects." (PMID 30170620, 2018). "To confirm necrosis in tumors, we analyzed TNF‐α expression in tumor sections by IHC." (PMID 29178186, 2018). "TNF-α itself is produced in the tumor microenvironment and regulates the communication between tumor cells, their surrounding stromal cells and the extracellular matrix in several cancers, acting as an autocrine and paracrine growth factor stimulating further expression of other growth factors." (PMID 30002278, 2018). "All these data suggested that tumor growth could influence the production and secretion of serum IL-2, TNF-α and IFN-γ, while PPs could enhance the immune function by stimulating the expression of serum cytokines in S180-bearing mice." (PMID 30966454, 2018). "However, combined treatment with IL-12 and TNFα resulted in a pronounced tumor growth delay of 27 days (calculated for the 3 mice that did not regress)." (PMID 29468364, 2018). "It is also worth mentioning that TNF-α may be related to cancer development and metastasis in certain tumor microenvironments." (PMID 29467927, 2018). "Tumor necrosis factor is abundant in any tumor microenvironment." (PMID 29892300, 2018). "Additionally, TNF-α is key to the defence against tumour cells through the induction of other immunoregulatory and inflammatory mediators." (PMID 29459629, 2018). "In our results, TNFα was the highest fold increase compared to control both of which is consistent with the increase in Neutrophils seen in the tumor stroma and supports our previous observation that OSCC and neutrophils develop a paracrine co-stimulatory loop." (PMID 30018735, 2018). "Tumor-expressed markers, such as programmed death ligand 1 (PD-L1), inhibit both the T-cell and NK cell response, whereas downregulation of Fas and tumor necrosis factor (TNF)-related apoptosis-inducing ligand (TRAIL) dampens lymphocyte-mediated tumor cell apoptosis." (PMID 29724044, 2018). "Similarly, upon depletion of FAP in fibroblasts, only 2% of the injected tumor cells can develop into a solid tumor and the anti-tumorigenic effect is mediated through interferon-γ and TNFα, besides the recruitment of CD8+ T cells into the TME." (PMID 29883428, 2018). "The reports that monocytes co-cultured with tumor cells or supernatant of tumor cells demonstrated significant decrease in expression of apoptotic factors such as TNF-α while increased expression of IRAK-M further support induction of immune suppression in carcinogenesis." (PMID 29961900, 2018).
tumor (continued). "Interestingly, in animal models of IHP, correlations are seen between degree of tumor vascularization and tumor reduction, further suggesting that TNF-alpha mechanistically targets the tumor endothelium." (PMID 30170620, 2018). "Apart from their putative role promoting tumor growth, both angiotensins could also be responsible of the proinflammatory status found here, with increased levels of IL-6 and TNF-α, acting through their angiotensin receptors." (PMID 29373553, 2018). "As a group, the median time to neoplasm from anti-TNF cessation was 4.4 years." (PMID 29540190, 2018). "TNFα treatment increased the rate of tumor growth and matrix degradation of both cell lines." (PMID 30356830, 2018). "TNF-α correlated with M1 macrophages in the stroma (r = 0.34; P < 0.05) as well as with the total number of M1 macrophages (r = 0.33; P < 0.05) and M2 macrophages in the tumor islets (r = 0.24; P < 0.05)." (PMID 29361917, 2018). "GBM neurosphere engraftment in nude mice followed by the infusion of a third generation CSPG4-CAR T-cell demonstrated lasting efficacy and minimal antigen escape, at least partially due to the upregulation of CSPG4 on tumor cells by microglia-derived TNF-α in the tumor microenvironment." (PMID 30740109, 2018). "It is intriguing to speculate that it might be the cytokine production within the tumor microenvironment that causes the expression of ICAM1 in the tumor cells, since TNFα and IFNγ are known to induce synthesis of ICAM147." (PMID 30082828, 2018). "N1 neutrophils have potent anti-tumor activity mainly due to their release of pro-inflammatory or immunostimulatory cytokines, such as interleukin (IL)-12, tumor necrosis factor (TNF)-α, CCL3, CXCL9, CXCL10, which facilitates recruitment and activation of CD8+ T cells." (PMID 30473691, 2018). "Several studies using immunoassays in colorectal tissue and in vitro cultures demonstrate that Fn infection increases the expression of inflammatory cytokines in tumor tissue, including IL-6, IL-8, TNF-α, and Cox-2, and these cytokines are capable of promoting tumor development." (PMID 30544946, 2018). "meso-CART cells secreted high levels of interferon-γ (IFN-γ), interleukin-2 (IL-2), and tumor necrosis factor-α (TNF-α) in response to mesothelin+ tumor cells (Aspc-1-meso, Skov3-meso, Panc-1-meso, and Capan-2), but not mesothelin- cells (Aspc-1, Skov-3, and Panc-1)." (PMID 29568387, 2018). "In classically activated macrophages, archazolid selectively induced the generation of tumor necrosis factor α (TNFα), which may indirectly promote tumor suppression." (PMID 30204757, 2018). "However, caloric restriction or reduction of TNFα and IL-6 leads to reduced tumor development in humans and mice by reducing colorectal inflammation." (PMID 30591653, 2018). "Over the last decades it has been extensively reported that tumor associated macrophages are able to promote tumor cell migration thought secretion of matrix-remodeling proteins, cytokines and chemokines (e.g. MMP-2, MMP-9, TNF-α, VEGF, TGF-β, EGF)." (PMID 29728948, 2018). "Interestingly, TNF-α itself has been shown to regulate the communication between tumor cells, their surrounding stromal cells and the extracellular matrix in several cancers." (PMID 30002278, 2018). "TNF-α is a pro-inflammatory cytokine that is cytotoxic for tumor cells." (PMID 30365491, 2018). "Thus, our findings demonstrate a TNFα + TGFβ1-driven pro-inflammatory fate in MSCs, identify specific molecular mechanisms involved, and propose that TNFα + TGFβ1-stimulated MSCs influence the tumor niche." (PMID 28553282, 2017). "In this model, tumor antigen-reactive CD8+ T cells activate Tip-DCs that in turn present tumor-associated antigens, thereby enhancing T cell expansion and tumor killing via TNFα and nitric oxide production." (PMID 28223985, 2017).
tumor (continued). "Utilizing the known differential therapeutic efficiencies of SL7207 and probiotic E. coli (Symbioflor-2), we asked if recombinant TNF-α may boost BMTT in more rigid tumor models." (PMID 28445131, 2017). "The presence of a variety of factors including inflammatory cytokines [TNF-α, CXCL8 (interleukin-8), and CXCL1 (GRO-α)] have been implicated in mediating both innate and acquired resistance to taxanes and/or platinating agents in tumor cell lines." (PMID 28915246, 2017). "However, if these tumors also express RasV12 the tumor cells hijack this macrophage response for their own gain such that macrophage-secreted TNF-α leads to tumor overgrowth and invasion." (PMID 28171746, 2017). "However, when produced chronically, TNF-α seems to act as a tumor promoter, contributing to the tissue remodeling and stromal development necessary for tumor growth and spread." (PMID 28983080, 2017). "It has been reported that various kinds of cells can release TNF-α, such as fibroblasts, Kupffer cells, keratinocytes, the infiltrating inflammatory cells, including tumor-infiltrating macrophages, and tumor cells which including B-cell lymphoma and colon carcinomas cells." (PMID 28938560, 2017). "However, there was a significant effect of tumor cell type on IL-1β (H = 29.44, p < 0.0001), IL-6 (F2, 37 = 13.68, p < 0.0001), TNFα (F2, 38 = 26.73, p < 0.0001), and CXCL1 (H = 10.86, p < 0.005)." (PMID 28811490, 2017). "Analysis of the correlations between TNF-α -308 G>A polymorphism and clinical features of CRC revealed that TNF-α -308 A allele was associated with higher body mass index (BMI) larger tumor size, and distant tumor metastasis in all CRC patients." (PMID 28575042, 2017). "The current study was intended to better understand drug-induced TNF-α production in tumor cells, whether from short-term drug exposure or in cells selected for drug resistance." (PMID 28915246, 2017). "Similarly, pro-inflammatory cytokines such as IL-6 and TNFα that are also present in the OC microenvironment, support tumour progression by influencing angiogenesis and tumour infiltration with myeloid cells." (PMID 28410380, 2017). "For example, CD8+ tumor-infiltrating lymphocytes exhibit high proliferation and IL-2/tumor necrosis factor (TNF)-α production in TC immunoreceptor with Ig and ITIM domain (TIGIT)−/− mice, indicating TIGIT inhibited the effector function and proliferation of CD8+ TC." (PMID 28738836, 2017). "Similarly, TNFα expression was high in the tumor tissue, and it was also generally higher in the livers of tumor-bearing mice compared to healthy controls." (PMID 28915665, 2017). "TNF signaling through TNFR2 promoted survival of MDSC helping tumor evasion." (PMID 28890718, 2017). "The antitumor effect of NGF was accompanied by an increase in the lymphocytic infiltration of the tumor tissue, the level of interleukin 1β and tumor necrosis factor α in the serum, as well as the activity of lactate and succinate dehydrogenases in tumor cells." (PMID 28878143, 2017). "Similarly, the level of IL-1β, IL-6 and TNF-α was also increased by APS in EAC tumor-bearing mice in vivo." (PMID 28303957, 2017). "TNF may promote tumor-induced lymphangiogenesis by up-regulating the expression of VEGF-C and VEGF-D, and this cytokine has also been shown to facilitate lymph node metastasis by promoting epithelial-to-mesenchymal transition." (PMID 28624797, 2017). "However, more recent evidences suggest that TNFα also has pro-tumor activities in a cell context-dependent manner." (PMID 28900035, 2017). "We postulated that TLR4 knockout prevents the increase in circulating cytokines that could stimulate muscle catabolism such as TNFα, IL-6 and IL-1β, and determined the effect of TLR4 deficiency on circulating cytokines in LLC tumor-bearing mice." (PMID 28536426, 2017). "Similarly, in OC, autocrine production of TNF-α within a tumor stimulates a constitutive network of cytokines, chemokines, and angiogenic factors in the stroma." (PMID 28725636, 2017).
tumor (continued). "Both IL-1β and TNFα are present in the tumor microenvironment." (PMID 29113326, 2017). "This might be due to the internal tumor necrosis and the pro-inflammatory environment, which promotes overexpression of TNF-α and activation of NF-κB pathway in later stage of tumor." (PMID 28774312, 2017). "Interestingly, aside from myeloid-based cells, non-tumor cell lines of human origin tend to be poorly responsive to taxanes in terms of TNF-α production." (PMID 28915246, 2017). "Tumor cells were treated with TNF in combination with TGF-β-type proteins and BMP4." (PMID 28423685, 2017). "Although the clinical application of TNF-α has been limited by its toxicity and side effects, preclinical and clinical studies have shown that these effects may partially be avoided via tumor-targeted delivery strategies." (PMID 29202842, 2017). "This suggested that Abnormal Savda Munziq may diminish the inhibiting effect of TGF-β1 on IFN-γ and TNF-α in PBMC, thereby increasing the concentration of TNF-α and enhancing anti-tumor effects." (PMID 28388901, 2017). "Explanations may still include local induction of TNF-α in the tumor or induction of alternate cytokines that may add therapeutic effects." (PMID 28445131, 2017). "Collectively, these experiments show that delivery of siRNA therapeutics guided by the affinity interactions between the tumor-homing peptide iRGD and cell-surface αv integrins and neuropilin-1 resulted in potent suppression of TNFα secretion in a receptor-specific fashion." (PMID 29018206, 2017). "The role of TNFα on tumor growth and migration was examined in vitro." (PMID 28160574, 2017). "In addition, treatment with laminarin among tumor-bearing mice increased production of IL-6, IL-12p40, and TNF-α in serum." (PMID 28423736, 2017). "We further examined whether inhibition of TNF-α was involved in CM2-driven invasive behavior of tumor cells." (PMID 28170411, 2017). "To further investigate the impact of factors released by TNFα + TGFβ1-stimulated MSCs on tumor cell motility, we determined the scattering of MCF-7 cells from spheroid tumor masses, demonstrated by our published study to correlate with a more aggressive behavior of the cells." (PMID 28553282, 2017). "Furthermore, the treatment of LPS-CuS with laser irradiation promoted up-regulation of IL-6, IL-12p40, and TNF-α mRNA levels in tumor drLN." (PMID 29285274, 2017). "The release of soluble factors, such as TNF-α, from tumor cells may be of importance in chemotherapy response, with and without the involvement of the host immune system." (PMID 28915246, 2017). "Notably, a synergistic action of IFN-γ and TNF-α was reported in early studies showing tumor growth inhibition in mice and tumor disappearance in patients after local limb perfusions with IFN-γ and TNF-α in combination with a chemotherapeutic agent." (PMID 29276511, 2017). "The differences in tumour progression observed in age-matched animals may in part be explained by a reduction in tumor IL-6, pSTAT3 and TNFα levels; suggesting that the tumour cytokines play a role in AT1R-mediated tumorigenic functions." (PMID 28416734, 2017). "At the same time, there were more TNF-α and IL-6 positive cells in tumor-adjacent tissues than that in control lung tissues, which suggests that tumor-adjacent cells surrounding the adenocarcinoma may also contribute to TNF-α and IL-6 production." (PMID 28801561, 2017). "A number of tumor cells are resistant to TNFα, which is mostly due to NF-κB activation." (PMID 28199969, 2017). "The levels of IL‐1, TNF‐α and IL‐6 in the tumour were also detected." (PMID 28444871, 2017). "TNF-α may directly damage DNA, mediate tumor and stromal cell interactions, inhibit apoptosis, promote cell proliferation, and induce expression of tumor development-promoting molecules." (PMID 28030810, 2017).
tumor (continued). "In both the in vitro tumor spheres and the in vivo murine model, there was a significant increase in the factors associated with M1 macrophage polarization, such as CCR5-binding chemokines (CCL3, CCL4, and CCL5), interleukins (IL-6 and IL-1β), and TNF-α." (PMID 28670313, 2017). "High levels of TNF-α can lead to anticancer effects through activating T cell-mediated immunity, whereas low-level, chronic TNF-α produced by cancer cells and stromal cells may promote tumor growth and metastasis." (PMID 28955335, 2017). "Our findings strongly support a recent hypothesis where the inflammation amplifier was activated by the stimulation of cytokines, such as TNF-α and IL-6, resulting in the subsequent expression of tumor-related genes such as HIF1-α and SOD-230." (PMID 28801561, 2017). "However, MDA-MB-231 and A2780 tumor cells responded to all of the agents with statistically significant increases in secreted TNF-α levels." (PMID 28915246, 2017). "Tumor-secreted inflammatory mediators such as Interleukin 6 (IL-6) and Tumor necrosis factor α (TNF-α), can regulate host metabolism in multiple tissues, suggesting a possible role of an inflammatory state in mediating tumor-induced metabolic changes in the host." (PMID 28874144, 2017). "According to the report that the treatment with 10 ng/ml or 100 ng/ml TNF-α could induce the increase of cancer stem cell populations and tumor lymphangiogenesis." (PMID 28938560, 2017). "However, in vivo effects of TNF-α differ and comprise increased vessel permeability used to improve drug penetration and destruction of tumor vasculature leading to hemorrhagic tumor necrosis." (PMID 29276511, 2017). "In contrast to the SFV-Ifng construct, we did not incorporate the enhancer element into the SFV-Tnfa vector aiming to retain low levels of translated TNF-α if necessary since lower levels of TNF-α might be important for normalization of tumor vasculature." (PMID 29276511, 2017). "Moreover, a recent report demonstrated that the tumor-enhancing activities of TNFα-primed adipose tissue-derived MSCs are mediated by TGFβ1, suggesting close interactive relationships between these two seemingly opposing cytokines." (PMID 28553282, 2017). "TNF-α is produced at low picogram levels in the tumor microenvironment, whether by tumor or stromal cells." (PMID 28030810, 2017). "The systemic administration of immunostimulatory agents, such as the synthetic TLR3 agonist poly(I:C) injected intraperitoneally (i.p.)or the oncolytic virus VSVΔ51 administered intravenously (i.v.), induced the production of cytokine TNF-α in the serum and brain of non-tumour bearing mice." (PMID 28198370, 2017). "M2 cells develop defective NF-κB activation during tumor progression by constitutive formation of p50 homodimers, leading to a reduced expression of iNOS accompanied by an impaired ability to produce NO and a reduced TNF-α secretion." (PMID 28804688, 2017). "Prophylactic treatment with Losartan resulted in an anti-inflammatory response mediated by reduced IL-6 and TNFα production, which prevented the differentiation of tumor stroma and epithelial cell EMT, and attenuated the malignant transformation of DCIS to IDC." (PMID 28416734, 2017). "The extracts increased the spleen index and thymus gland index of tumor-bearing mice, promoted the proliferation of T lymphocytes, enhanced the phagocytotic function of macrophages, and up-regulated the levels of IL-2, IL-6, IL-12, and TNF-α." (PMID 28919922, 2017). "In C57BL/10J (TLR4+/+wild-type) and C57BL/6J (MyD88+/+wild-type) tumor-bearing mice, the tumor apoptosis rate, immune organ indexes and the levels of TNF-α, IL-1β and IL-6 in blood increased and the tumor weight decreased by oral administration of APS for 25 days." (PMID 28303957, 2017).